RNU6-516P (RNA, U6 small nuclear 516, pseudogene)
Gene: Small nuclear RNA gene on chromosome 15 (40,529,570 to 40,529,673, forward strand). Ensembl gene ENSG00000223313.
Homologues: Orthologues: chimpanzee U6 (99% identical), macaque U6 (81% identical). Paralogues in human: RNU6-14P (78% identical), RNU6-333P (78% identical), RNU6-1 (77% identical), RNU6-15P (77% identical), RNU6-2 (77% identical), RNU6-25P (77% identical), RNU6-33P (77% identical), RNU6-3P (77% identical), RNU6-48P (77% identical), RNU6-4P (77% identical), RNU6-549P (77% identical), RNU6-5P (77% identical), and 1285 more.